Y_RNA (Y RNA )
Gene: Miscellaneous RNA gene on chromosome 10 (73,192,223 to 73,192,325, reverse strand). Ensembl gene ENSG00000199201.
Homologues: Orthologues: chimpanzee Y_RNA (98% identical), macaque Y_RNA (95% identical), guinea pig Y_RNA (86% identical). Paralogues in human: RNY3P2 (88% identical), Y_RNA (87% identical), RNY3 (86% identical), Y_RNA (86% identical), Y_RNA (85% identical), Y_RNA (84% identical), RNY3P1 (83% identical), RNY3P14 (83% identical), Y_RNA (83% identical), RNY3P16 (82% identical), RNY3P9 (82% identical), Y_RNA (82% identical), and 94 more.